APOE (apolipoprotein E)
Diseases named in the same sentence as APOE in open-access papers (continued):
Sharing a sentence is not in itself a finding about the gene and the disease.
dyslipidemia (continued). "To exclude the possibility that KC ablation prevented atherogenic dyslipidemia as an alternative explanation for this lack of liver response, we measured plasma and liver lipids in both APOE cKO and D374 strains." (PMID 39196121, 2024). "Taken together, these data demonstrated that the ApoE KO mouse fed with WD is a great model for NASH research, once it presents the fundamental parameters of the disease, including hepatic steatosis, fibrosis, inflammation, and metabolic syndrome." (PMID 36286035, 2022). "APOE*3-Leiden.CETP mice, as part of an inbred mouse model in which mice develop the metabolic syndrome upon being fed a high-fat high-cholesterol diet, show large inter-individual variation in the parameters of the metabolic syndrome, despite a lack of genetic and environmental variation." (PMID 36432620, 2022). "After being fed with a high-cholesterol diet (HCD) for 12 weeks, the ApoE KO rats displayed typical dyslipidemia, although there was no obvious atherosclerotic lesion in the en face aortas." (PMID 35269691, 2022). "Compared to those of the model group, the levels of TC, TG and LDL in the ApoE group were further increased (p < 0.01), suggesting that the absence of ApoE aggravated dyslipidemia in aging mice." (PMID 36188475, 2022). "In addition, CCQS-specific and QSBS-specific genes were also enriched in metabolic Syndrome and cerebrovascular disease, respectively, in which Syndrome-specific DPs involved in the diseases were PON1 and ADIPOQ for CCQS, APOE and APOA1 for QSBS." (PMID 34702323, 2021). "Taken together, we found that dyslipidemia in these mice failed to explain the reason why the aged ApoE-/- mice suffered more severe AS lesions than the young mice." (PMID 33816331, 2021). "Dyslipidemia in total cholesterol, triglycerides, low-density lipoprotein cholesterol, apolipoproteins(apo) B and apoE increased with OSA severity, but only in non-obese subjects and those <55 years of age." (PMID 28134311, 2017). "In contrast, no obvious relationship between APOE status and serum triglycerides was reported in a study with patients with metabolic syndrome, which is in line with our findings." (PMID 29233125, 2017). "Fifty-eight cognitively healthy men, 28 IR and 30 non-IR (age and APOE ε4 matched), were drawn from the Metabolic Syndrome in Men study in Kuopio, Finland." (PMID 28441961, 2017). "High-salt diet led to NASH in high-fat diet-fed LOX-1 transgenic/apoE knockout mice without affecting high-fat diet-induced dyslipidemia or hepatic triglyceride accumulation." (PMID 25888871, 2015). "In conclusion, salt overload may accelerate the accumulation of oxidative stress under the condition of HFD consumption and induce NASH in the liver in a dyslipidemia model, LOX-1 Tg and apoE KO mice." (PMID 25888871, 2015). "APOE−/− mice, lacking the key lipid metabolism regulator ApoE, exhibit phenotypic characteristics that are highly similar to those of human MS under high-fat diet stimulation, including significant insulin resistance, dyslipidemia and chronic inflammation." (PMID 40417212, 2025).
dyslipidemia (continued). "Although the previous work demonstrated dyslipidemia when dystrophic, ApoE knockout mice were fed this diet, IR was not considered, though some parameters of muscle injury were increased in gastrocnemius and tibialis brachii muscles but not diaphragm, quadriceps femoris, and cardiac muscles." (PMID 37811713, 2023). "However, the two groups did not significantly differ in dyslipidemia, sex, APOE ε4 carrier proportion, or BMI level." (PMID 34127075, 2021). "The interaction between ApoE ε4 and dyslipidemia on cognition is not yet completely understood." (PMID 32485802, 2020). "Furthermore, the components of dyslipidemia may differ between genders, e.g., males showed higher TG, LDL, and apoB and lower HDL, apoA-I, and apoE than females." (PMID 31093507, 2019). "The absence of dyslipidemia in these animals does not foster plaque growth, thus providing insights on proatherogenic mediators specifically associated with VDR deletion, without the direct effects of the proatherosclerotic (apoE-/-) genotype." (PMID 26322890, 2015). "Yet whether this is related to the dyslipidemia or a cell-type specific effect of the lack of apoE remains unclear." (PMID 26695075, 2015). "Therefore, ApoE-/- mice were used to establish a dyslipidemia model with a HFD approach, and the contents of the cecum of the mice were collected for a gut microbiota study and to analyze how the GLXB herbal pair ameliorates dyslipidemia through the gut microbiota in ApoE-/- mice." (PMID 41466480, 2025). "ApoE-mediated HSPC proliferative control was shown to be mediated through cellular lipid efflux via ABCA1 and ABCG1, as in their absence, pools of cell surface apoE no longer suppressed HSPC hyperproliferation in mice with dyslipidemia." (PMID 29789495, 2018). "While phospho-PKCβII is pathognomonic for glucose-mediated vascular damage, increased RAGE immunoreactivity was also detected in atherosclerotic lesions of non-diabetic ApoE-null mice, consistent with increased AGE/RAGE levels in response to the oxidative stress of dyslipidemia." (PMID 21151899, 2010).
Obesity (374 papers, 2008 to 2026). Accumulation of substantial excess body fat. "To clarify p16 and its role in obesity‐associated kidney fibrosis, we treated ApoE knockout (ApoE−/−) mice with a high‐fat diet (HFD) (containing 60% calories) for 6 months and recorded the weights of the mice every week." (PMID 40079088, 2025). "Both the findings in our two patients and their family, as well as those reported in literature, suggest that obesity is an important modifier of the severity of the phenotype in individuals who are either heterozygous or homozygous for the APOE-ε1 variant." (PMID 40149441, 2025). "Clinical studies must stratify participants by obesity phenotypes, leptin resistance status, metabolic comorbidities, and genetic risk factors such as APOE-ε4 to assess context-dependent adipokine effects." (PMID 41155642, 2025). "Increasing OSA severity was associated with greater obesity, more obvious dyslipidaemia, and higher levels of APOE and IR." (PMID 38956564, 2024). "Together, these findings highlight the importance of the APOE genotype as a modulator of the risks associated with obesity and the beneficial outcomes of estradiol." (PMID 39347015, 2024). "Of the three SNPs associated with both weight change and lifespan, two (rs429358 and rs7412) are variants in the APOE gene, and rs1085251 is a known obesity association in the FTO locus." (PMID 38987242, 2024). "In conclusion, the present study provides further evidence for the APOE/APOC1 candidate-region association with the risk of obesity, in particular in children." (PMID 37328602, 2024). "The overexpression of APOE has been shown to predispose mice to diet-induced obesity, hyperglycemia, and insulin resistance, suggesting generational obese mice (Wes(WES)) have a high propensity for developing hyperglycemia and insulin resistance." (PMID 39339686, 2024). "To examine the in vivo impact of ApoE deficiency on obesity development, we subjected the mice to HFD feeding." (PMID 38062308, 2023). "We found that ApoE deficiency protects mice from HFD-induced obesity; however, it is well-known that ApoE-/- mice show a marked increase in TC and TG." (PMID 38062308, 2023). "Previous studies have reported that the APOE ɛ4 allele can worsen the cognitive function in relation to obesity." (PMID 35921193, 2023). "APOE gene is the most common and strong genetic risk factor for AD, indicating that obesity is correlated with AD." (PMID 37686334, 2023). "APOE promotes lipid accumulation, and previous studies have demonstrated its association with obesity." (PMID 37371369, 2023). "Taken in aggregate, these findings propose a potential involvement of ApoE in the modulation of macrophages, consequently contributing to the pathogenesis of metabolic disorders associated with obesity." (PMID 38062308, 2023). "ApoE*ε2+ was significantly associated (p = 0.030, OR = 0.24, 95% CI 0.06–0.87) with overweight and obesity (BMI>25.kg/m2) and Castelli risk index (p = 0.024, OR = 11.26, 95% CI .37–92.30) in females." (PMID 37134097, 2023). "APOE genotype and obesity have been independently and interactively linked to AD risk, in humans and rodents." (PMID 37432149, 2023). "Our results suggest that the role of ApoE in regulating obesity and obesity-associated glucose dysregulation is inconsistent." (PMID 38062308, 2023). "In fact, in the literature, it is demonstrated that obesity is associated with polymorphisms of the APOE gene." (PMID 35573533, 2022). "More recently, apolipoprotein E3 in the brain has been associated with fat accumulation and obesity, and hepatically expressed apolipoprotein E3 has the opposite effect." (PMID 35205269, 2022). "Overall, several genetic variants in APOE has been widely related to pro-inflammatory measure, and obesity." (PMID 36088317, 2022). "APOE ε4ε4 was associated with a reduced prevalence of obesity (OR = 0.78), and ε2ε2 with an increased prevalence of obesity (OR = 1.22) compared with ε3ε3." (PMID 35205269, 2022).
Obesity (continued). "These mutations cause defective apolipoprotein E, protein phosphatase 1 like protein, lipoprotein lipase, and lactamase b, respectively, that are strongly associated with obesity." (PMID 35388304, 2022). "In this study, we showed that apoE-deficient rats present multiple organ damages besides the known predisposition for obesity and affected lipid metabolism." (PMID 34575848, 2021). "APOE genotypes have different metabolic profiles, with different susceptibilities to obesity and insulin resistance." (PMID 33383760, 2020). "Of the three isoforms of ApoE, ApoE4 is a prevalent risk factor that is synergistic with obesity and age for AD." (PMID 32581851, 2020). "Obesity during midlife is associated with an increased risk of dementia up to 74%, independently from hypertension, diabetes, APOE genotype and other cardiovascular risk factors." (PMID 33050475, 2020). "It is well known that male mice are more susceptible to diet-induced obesity than female mice, and this also holds true for APOE*3-Leiden.CETP mice (unpublished observations)." (PMID 32915671, 2020). "Cognitive functions are influenced by complex interactions of APOE genotype with obesity that differ by sex, age, and co-inherited gene variants." (PMID 32587511, 2020). "Except for a possible association between E4 and obesity, little is known about associations between APOE variability and morbidity in subjects with obesity." (PMID 32646381, 2020). "High-fat diets and ApoE deficiency are also suggested to impair the gut–brain barrier function involved in the onset of obesity and neuropathological disorders, including AD." (PMID 32344633, 2020). "The topic of this study is considered generally interesting and the reviewers acknowledge the careful examination of the interactions between Alzheimer (AD) risk factors ApoE and obesity as reflected by parameters genotype, diet and sex." (PMID 31554665, 2019). "Apolipoprotein E-deficient mice are resistant to diet-induced obesity, insulin resistance, and glucose intolerance." (PMID 31064116, 2019). "Few previous studies examining associations of the APOE isoforms with body fat traits reported associations of the ε4 allele with decreased obesity in less‐fitted children and non‐significant trend in mid‐aged adults." (PMID 30462377, 2019). "Both human studies and rodent models have contributed to understanding the effects of obesity on the different APOE genotypes, and we outline possible underlying mechanisms associated with these effects." (PMID 30586872, 2018). "Possibly, decreased APOE expression that is thought to facilitate obesity decreased risk of this disorder." (PMID 28163789, 2017). "ApoE was identified playing an important role in the development of obesity and insulin resistance in experimental mouse models, and the mutation in APOE was involved in lipid metabolism and lipid levels in population studies." (PMID 29132311, 2017). "In present study, the significant association of APOE genotype with hypoalphalipoproteinemia has been found before and after adjustment of obesity-related traits in Vietnamese primary school children." (PMID 27724906, 2016). "The results demonstrate that TSP1 deficiency improves metabolic phenotype of HF-fed ApoE-/- mice with reduced obesity-associated systemic inflammation and improved insulin sensitivity." (PMID 25803585, 2015). "In the current study, we utilized a proatherogenic and hyperlipidemic mouse model (ApoE-/- mice) to investigate the role of TSP1 in obesity associated vascular complications." (PMID 25803585, 2015). "In the current study, we utilized TSP1 and ApoE double knock out mice to investigate the role of TSP1 in obesity associated vascular complications in a high fat diet induced obesity mouse model." (PMID 25803585, 2015). "We determined the effect of TSP1 deficiency on the development of obesity-induced kidney damage (a microvascular complication) in ApoE-/- mice." (PMID 25803585, 2015).
Obesity (continued). "E2 allele of the APOE gene polymorphism was predictive for obesity status in Roma minority population of Croatia." (PMID 24456740, 2014). "Actually, it is hard to definitely evaluate ApoE polymorphism in obesity on account of almost unavailable ApoE2 and ApoE4 homozygous in humans." (PMID 25148848, 2014). "Deletion of ApoE in genetic mutation obese mice, such as leptin deficient mice and Ay/+ mice, also prevented diet-induced obesity by either a high-cholesterol diet or high-sucrose diabetogenic diet." (PMID 25148848, 2014). "Previous studies have shown that apoE deficiency prevents the development of obesity in B6 mice and genetically obese Ay mice on a high fat diet." (PMID 22204493, 2011). "In conclusion, APOE polymorphism is a major determinant of CVD risk in the Croatian Roma acting on several phenotypic risk traits - obesity indicators and lipid levels (LDL and triglycerides)." (PMID 21244662, 2011). "These will include the analysis of family data directed towards confirming linkage between APOE ε2, ε3, ε4 polymorphism and obesity phenotype." (PMID 21244662, 2011). "APOE alleles and genetic variants of IL-6 have also been established to be factors of susceptibility to obesity." (PMID 19804633, 2009). "Obesity is known to alter lipid homeostasis, leading to an increased amount of triglyceride-rich lipoprotein particles in plasma, which are known to be cleared less efficiently in patients with disruptive APOE variants." (PMID 40149441, 2025). "However, our MR study selected SNPs significantly associated with ADPN from the GWAS dataset and removed ADPN SNPs associated with age, obesity, inflammation, and APOE sites to minimize type I errors." (PMID 40371086, 2025). "The study suggests that vitamin D deficiency, along with APOE genotyping, may play a role in the risk of obesity and T2DM." (PMID 39138505, 2024). "However, no work, to date, has systematically examined the interactions of obesity and AD risk via APOE-ε4 in older African American adults." (PMID 37731955, 2023). "Thus, comparing the causal associations between obesity and different APOE phenotypes will be helpful in elucidating the relationship between obesity and AD." (PMID 37686334, 2023). "It was the first study to demonstrate a direct association between POCD and obesity and to suggest that APOE-ε4-allele in obese patients may be a cognitive deterioration mechanism." (PMID 37497308, 2023). "In contrast, among APOE-ε4 carriers, obesity is associated with smaller CA1 volumes." (PMID 37731955, 2023). "Furthermore, ApoE mRNA level was negatively correlated with BMI value (r = −0.398, P = 0.0056), indicating that ApoE inversely associated with obesity progression." (PMID 38062308, 2023). "Furthermore, we found that ApoE deficiency mice globally prevented obesity by restraining adipose tissue expansion and improved systemic glucose tolerance and insulin sensitivity." (PMID 38062308, 2023). "That genetic and health risk factors (i.e., obesity) synergistically affect CA1 subfield volume may help explain why African Americans–who have higher prevalence of both the APOE-ε4 allele and obesity–are more likely to develop AD." (PMID 37731955, 2023). "The mechanism for the association of APOE with obesity and body fat mass is speculated to be attributed to its role in regulating the expandability and functionality of adipose tissues." (PMID 36276968, 2022). "In addition, it is likely that obesity effects will be modulated by other polygenic risk factors than APOE ε4." (PMID 35303671, 2022). "Knowing that some APOE alleles are associated with obesity and endocrine disorders that are common in obesity, the present study aimed at exploring associations between APOE polymorphisms and endocrine functions in subjects with obesity undergoing bariatric surgery." (PMID 35205269, 2022). "Current literature on the relationship between APOE polymorphism and obesity risk is controversial." (PMID 36077289, 2022).